MIR4737 (microRNA 4737)
Synonyms: hsa-mir-4737
Gene: MicroRNA gene on chromosome 17 (60,043,025 to 60,043,105, reverse strand). Ensembl gene ENSG00000264049.
Diseases named in the same sentence as MIR4737 in open-access papers:
MIR4737 is named in the same sentence as 1 disease in open-access papers, as found by Europe PMC text mining. Sharing a sentence is not in itself a finding about the gene and the disease. The quoted sentences say what the papers report.
tumor (1 paper, 2025). "Many ncRNA-based genes, such as MIR4737, CR381653.1, and SNORD19, are among the genes specifically expressed in TICs, suggesting the functional importance of ncRNAs in tumor initiation and stemness maintenance." (PMID 40862733, 2025).